TNF (tumor necrosis factor)
Diseases named in the same sentence as TNF in open-access papers (continued):
Sharing a sentence is not in itself a finding about the gene and the disease.
infection (continued). "For example, C3H/HeN mice depleted of either IFNγ or TNFα showed enhanced disease upon infection with a dose of R. conorii that normally does not result in symptomatic disease and similar observations were made for R. typhi infection of C3H/HeN mice." (PMID 27875529, 2016). "As observed, ST2−/− mice had higher levels of TNF-α and IFN-γ transcripts locally (at the CNS) when analyzed 9 days post-infection (when disease symptoms are evident on ST2−/− mice); systemically (serum cytokines), the production of these cytokines were also increased, when compared to WT mice." (PMID 27334012, 2016). "There are four proinflammatory cytokines: tumor necrosis factor-alpha (TNFα), lymphotoxin alpha and beta (LTA and LTB), and leukocyte specific transcript-1 (LST1) in the class III region that are important in inflammation and infection." (PMID 27812316, 2016). "The significant parameters for the non-clearance outcomes suggest a more macrophage/TNF centric response to infection, with reduced pro-inflammatory response when compared to clearance outcomes." (PMID 26913242, 2016). "Moreover, increased levels of major pro-inflammatory cytokines IL-6, TNF-α and chemokine MCP-1, have been demonstrated from the murine lung epithelial cell line, primary lung epithelial cells and an inhalational murine infection model." (PMID 27529172, 2016). "Thus, BCG vaccination alters the ensuing polyfunctional profile upon infection with virulent M. bovis, favoring early IFN-γ/TNF-α/IL-2 production by CD4+ Tcm cells and dampening TNF-α/IFN-γ elicited by infection." (PMID 27799930, 2016). "The molecules that depicted significant increases in those mAb treated-mice at 96 h after infection were CXCL1 (KC), CCL2 (MCP-1), CCL3 (MIP-1α), CCL4 (MIP-1β), CXCL2 (MIP-2), CXCL5 (LIX), IL-1α, IL-6, G-CSF, M-CSF, and TNF-α (for all, P < 0.01) and IL-1β, IL-15, IL-10, and LIF (for all, P < 0.05)." (PMID 27642235, 2016). "Whereas the secretion of IL-6 by spleen cells was unaffected by the lack of IL-22, the splenic production of IFN-γ, TNF and IL-10 was increased in IL-22−/− mice compared to wild-type mice at day 14 post infection." (PMID 27650379, 2016). "No statistical difference was found in the serum TNF-α levels among diabetic mice in neither the infection nor the shame-infection groups (P > 0.05)." (PMID 27995146, 2016). "As an illustration, IFN-γ and TNF, which are required for cure of infection in mouse models, do not prevent ulceration in humans and actually correlate with the development of disease." (PMID 27167379, 2016). "Infection of Tnfr1-/- BMDMs established that MtbΔRv3167c-induced necrosis was independent of TNF signaling." (PMID 27191591, 2016). "Several cytokines produced by T cells (IFNγ or TNF35, 36), myeloid cells (IL-1, IL-12, TNF, IL-6 32, 37, 38, 39, 40) or epithelial cells (GM-CSF41) are ascribed crucial roles in host resistance based on the early mortality of knockout mice following infection." (PMID 27819295, 2016). "TNFα and IL-10 concentrations were slightly higher following infection with 6B rather than 7F but not significantly, although significantly higher than the non-encapsulated mutant." (PMID 27009189, 2016). "METH did not alter the expression pattern of IL-2/IFN-γ/TNF-α in the CD8 T cells during the entire course of infection." (PMID 27760221, 2016). "For example, Beltan and the coworkers revealed a considerable induction of the synthesis of the proinflammatory cytokines IL-1, IL-6, GM-CSF, and TNFα after in vitro infection of human macrophages with only nonpathogenic mycobacteria." (PMID 27066505, 2016). "Furthermore, we found a significant increase in the concentration of IL-1β and TNF-α in the brain of mice with low-grade CLP 3 days after surgery, indicating an infection-initiated neuroinflammation." (PMID 27270556, 2016).
infection (continued). "No significant variations were observed for IL-1β and TNF-α expression in the acute infection model even if a trend for increase was observed for both the cytokines mRNAs in the presence of S. aureus after 9 h." (PMID 27446812, 2016). "In order to investigate the effect of short-term heat shock on HSP70 expression in H5N1-infected mice, we detected the expression of HSP70 as well as cytokines including IL-6, TNF-α, IFN-β, and IFN-γ with real-time PCR, western blot, and ELISA at Days 0, 1, 3, and 6 post-infection." (PMID 27379054, 2016). "TNF-α levels in hamster BAL samples were significantly higher at the peak of disease than at earlier time points (day 17 versus day 10), but AMθ depletion affected TNF-α expression only early after infection." (PMID 27099308, 2016). "The second finding from prospective analyses concerned elevated non-specific TNF responses at inclusion that were a prognostic marker for subsequent infections." (PMID 27653505, 2016). "Starting from the first day of severe infection caused by 103 PFU Absettarov strain, no TNF-α or IL-2 were detected in sera of infected mice." (PMID 28163697, 2016). "Contrary to TNF-α treatment, IFN-α treatment significantly suppressed the mRNA levels of the Ad early genes, including the E1A, E2, E3, and E4 genes, in HeLa cells following infection with WT-Ad." (PMID 26814140, 2016). "From a diagnostic perspective, we reasoned that TNF-α should distinguish between patients with SIRS and without SIRS (non-SIRS) while CRP should perform best at distinguishing infection (VAP) from no infection (non-VAP)." (PMID 28469676, 2016). "Infections with P. falciparum detected at inclusion were associated with enhanced non-specific TNF responses, whilst diminished non-specific and DBL-5-specific IL-10 responses were associated with infections detected at delivery." (PMID 27653505, 2016). "The levels of TNF-α, IL-6 and IFN-γ tended to increase gradually as infection progressed." (PMID 27489303, 2016). "Tumor necrosis factor-alpha (TNF-α) plays a pivotal role in the defense against infection with this Gram-negative coccobacillus." (PMID 27656302, 2016). "In parallel, after secondary Pseudomonas (gram negative bacteria) infection, mice exhibit similar reactivation of pro-inflammatory mediators such as TNFα in CLP and Sham." (PMID 27574993, 2016). "WT PR8 infection induced higher levels of proinflammatory cytokines, such as TNF-α, CXCL12, and interleukin 6 (IL-6), than infection with the segment 8 reassortant viruses, while the profiles in O175A- and O265B-infected mice were more similar to each other than to the profile in PR8-infected mice." (PMID 27489273, 2016). "TNF-α/IL10 plasma ratio measured shortly after burn trauma was inversely correlated with burn size and the injury severity scores investigated, and was predictive of repeated infections (≥3 infection episodes) outcome (AUROC [95%CI] of 0.80 [0.63–0.93])." (PMID 27761434, 2016). "A significant reduction of the level of the pro-inflammatory cytokine TNF-α (2nd sample) in patients with SAI than in those without infection (P = 0.000) was also observed in our study." (PMID 27453748, 2016). "Also, when S. tmAvir was used for the secondary infection in AIEC-colonized mice there was a significant reduction in immunopathology, a blunted TNFα release from explanted cecal tissue, and a significant reduction in fecal lipocalin-2 output." (PMID 27711220, 2016). "We noticed that a comparable percentage of the pp65-CTL became activated as assessed by IFNγ and TNFα intracellular cytokine staining, independent of which virus was used for the infection of DC." (PMID 27907183, 2016). "A cohort of cynomolgus macaques with LTBI (n = 26) was PET CT imaged at least 6 months post-infection, immediately prior to being randomly assigned to receive either TNF neutralizing antibody for 5–8 weeks or no treatment." (PMID 27379816, 2016).
infection (continued). "However, in our infection model, at late times some factor(s) from EAEC decreased p65 phosphorylation and this inhibition was kept in TNF-α-induced p65-phosphorylation." (PMID 27774437, 2016). "Previous studies have demonstrated that endogenous TNF plays an important role in host resistance to S. aureus infection, while endogenous IFN-ɤ provides protection in the early stage of infection and plays a detrimental role late in infection." (PMID 27446000, 2016). "Correspondingly, we noticed little difference in the amount of TNF-α in the BAL fluid of hamsters in the presence or absence of AMθ following infection with ANDV intramuscularly or at late times after intranasal infection." (PMID 27099308, 2016). "To clarify the role of Dectin-2 in the host response to S. pneumoniae infection, we compared the production of proinflammatory cytokines and chemokines, such as IL-1β, TNF-α, IL-6, IFN-γ, IL-17A, and MIP-2, in BALF between WT and Dectin-2KO mice 12 h after infection." (PMID 26727976, 2016). "In our analysis, we observe that a subset of these cytokines reported to be present in the serum also show transcriptional upregulations in PBMCs by 4 days post-infection (IL6, IL1B, IL1RN, CCL8, CXCL10) and by 7 days post-infection (CCL2, CCL3, CSF1, TNF, CXCL1, FAS and CXCL8)." (PMID 27595844, 2016). "After 60 h of infection, at the more acute phase, the bacteria had induced a substantial increase in the expression of genes for most proinflammatory cytokines, including IFN-γ, IL-1β, IL-2, IL-6, IL-8, IL-22, and TNF-α, as well as genes for IL-10 and IL-4." (PMID 27357336, 2016). "The up-regulation of both TNF-α and IFN-γ mRNA suggests that STAT3 represses inflammatory cytokine production at the transcriptional level, limiting acute inflammation at the site of infection." (PMID 27384401, 2016). "We therefore interrogated the diagnostic and prognostic value of both CRP and TNF-α in enhancing the clinical distinction between 1) critically ill patients with and without a clinically defined SIRS, and 2) with and without infection." (PMID 28469676, 2016). "Particularly TNF-α expression levels were massively elevated by the infection (60.497-fold in the group without E2 pre-treatment, 322.568-fold in the low E2 pre-treatment, 5651.008-fold in the high E2 pre-treatment group)." (PMID 26821056, 2016). "TEM cells, which appear early after infection and can secrete effector cytokines such as IFN-γ and tumor necrosis factor alpha (TNF-α), provide immediate protection, while TCM cells proliferate in the LN and generate new waves of effector cells upon reexposure to antigen." (PMID 27222470, 2016). "We found that TNF-α and IL-1β levels were below the detection limit for most of the days after infection (data not shown) for both high dose (1000 TCID50) groups treated with oseltamivir either prophylactic or therapeutic regimen." (PMID 27110056, 2016). "After initial Leishmania infection of macrophages and dendritic cells, these cells produce proinflamatory cytokines and chemokines, such as TNF-α and CXCL-10, that in turn recruit new host cells (natural killer cells (NK), monocytes and neutrophils) to the infection site." (PMID 27668434, 2016). "Moreover, infection induces DC maturation and increases expression of β3 integrin, interferon (IFN)-α and tumor necrosis factor (TNF)-α." (PMID 27529272, 2016). "The notion that IFN-γ is necessary but not sufficient for bacterial control after infection is also supported by several studies in knockout mice for TNF-α, granulocytes, GM-CSF, IL-1, and IL-6, as they also die rapidly after M. tuberculosis infection." (PMID 26495323, 2015).
infection (continued). "Pulmonary and splenic infection was established early in the absence of TNF and bacilli burdens significantly higher than TNFf/f or NsTNF−/− mice, indicating that TNF is required to control early dissemination of infection." (PMID 26112704, 2015). "Specifically, TNF-α, GM-CSF, MIP-1α, IL-1α, IL-1β, IL-2, IL-3, IL-12p40, IL-12p70, and IL-17 levels were significantly reduced in UV-12 animals compared to vehicle control treated mice at both the 72 and 96 h post infection time points." (PMID 25984714, 2015). "Similar to our murine macrophages findings, M-CSF-matured hMDMs were highly permissive for EBOV GP/rVSV infection and human IFNγ, but not TNFα, effectively and profoundly blocked the number of cells infected by our recombinant virus." (PMID 26562011, 2015). "For all of them, a peak induction of TNF-α and/or MCP-1 was observed at day 7 post-infection." (PMID 26197047, 2015). "When macrophages were incubated with magnesium particles and then infected with the apathogenic Mycobacterium smegmatis, infection-induced TNFα secretion from murine macrophages was inhibited but not from human macrophages." (PMID 29470790, 2015). "A careful dissection of the transcription profile by day 1 pi in tissues from E75CV1-infected pigs, allowed the confirmation of the significant up-regulation of CD163, IL-1β, IFN-γ, IL-5, IL-6, IL-10, IL-12p40, TNF-α and TGF-βR1 and the down-regulation of DEFB2, immediately after E75CV1 infection." (PMID 26589145, 2015). "Besides TNF-α, the induction of other cytokines including IL-6 and IL-1β was also observed in both Huh7 cells and PHH at 2 hours post-infection." (PMID 26023919, 2015). "In the absence of TNF-α the number of live cells was only affected by the highest R7020 infection level, 10 MOI, decreasing it by 16 and 42% relative to control at 24 and 72 h p.i., respectively." (PMID 26132411, 2015). "Based on our computed results, we concluded that a Healing Process occurs when the level of pathogens, level of phagocytic cells (neutrophils and monocytes), and level of inflammatory cytokines (TNF-α, HMGB-1, and IL-10) oscillate below threshold during infection." (PMID 26446682, 2015). "With the progression of the infection a more equilibrated immunological balance is observed, with 6 genes showing significant transcription up-regulation: IFN-γ, IL-5, TNF-α, TGF-βR1, IL-21 and IL-23 and 4 extra genes showing significant down-regulation: DEFB1, CD163, IL-13 and IL-18." (PMID 26589145, 2015). "However, when the MOI of 1 was used, the fold induction of TNF-α at 2 hours and 24 hours post-infection was similar at about 15, indicating a dose-effect of HCV on the induction of TNF-α at the early time points of infection." (PMID 26023919, 2015). "UV-crosslinking had no impact on antibody-dependent signaling at 4 hours post infection but TNFα transcription at 8 hours was substantially reduced." (PMID 26506431, 2015). "In this sense, the action of PLA2 impeded the parasite from maintaining its escape mechanism, a fact also observed in a prior study that measured the production of TNF-α, NO, and IL-10 in treatment with PLA2 from B. pauloensis in experimental infection of murine macrophages with L. amazonesis." (PMID 26609302, 2015). "In the absence of the pro-inflammatory cytokine TNF the protection against L. major is severely impaired resulting in a progressive infection and eventually a fatal outcome." (PMID 26834705, 2015). "TNF-α mediated nuclear translocation of NF-κβ p65 subunit is partially blocked by SchuS4 but not LVS infection." (PMID 26510639, 2015). "In contrast, NFκB activation during infection of AdV alone was only observed at an MOI >100, although induced TNFα transcription could be detected at slighter lower viral doses." (PMID 26506431, 2015).
infection (continued). "Our data showed a positive correlation between the expression of TNF-alpha and the expression of Granzyme A. Interestingly, this correlation was only observed after the infection with Y strain and not in media or infection with Col cl1.7." (PMID 26147698, 2015). "Overall, in spleen the production of Th1 cytokines (such as IFN-γ, IL-12 and TNF) of both asymptomatic and symptomatic dogs does not show any differences, however they are increased during infection." (PMID 25875101, 2015). "The dramatic increase found in sera of almost all the immune mediators tested: TNF-α, IFN-α, IL-12, IL-1β and sCD163 confirm the soluble factor storm suffered by acutely infected pigs in the latter phases of infection, most probably reflecting the massive tissue destruction found." (PMID 26589145, 2015). "In the context of the host response, infection of mouse macrophages with Mtb pre-grown in reduced (500 μM) Mg2+ media resulted in a 2-fold increase in TNF-α production by macrophages infected with perM::tn, but not wt or complemented strains." (PMID 25658098, 2015). "The serum concentration of IFNγ, TNFα, IL-10 and IL-6 only started to increase substantially on day 6 post-infection, and no apparent difference was observed in the serum levels of IL-1β." (PMID 25768944, 2015). "Expectedly, infection of P.a (2.5×106 CFU/mice), resulted in a sharp increase in neutrophils associated with increased levels of KC, IL-6, TNFα, IL-1β and IL-12 in BAL fluids compared to non-infected mice." (PMID 25605549, 2015). "Speculatively, elevated TNF-α and reduced IL-10 in avian influenza virus infected PAM could indicate a more balanced paracrine/endocrine pro-inflammatory signature during infection." (PMID 26642934, 2015). "Lipopolysaccharides (LPS) are an endotoxin that mimics infection by gram-negative bacteria by activating the immune system to release proinflammatory cytokines, such as tumor necrosis factor α (TNF-α), interleukin-1β (IL-1β), and IL-6." (PMID 25775356, 2015). "At 30 h post infection, IL-10 and KC levels were lower in C/EBPδ−/− brain homogenates, whereas brain IL-6, TNF-α, IL-1β, and MIP-2 levels were not significantly different between the two genotypes." (PMID 25958220, 2015). "However, synergistic effects of IL-1β and TNF-α (IL-1β+TNF-α) seemed to be significant for which substantial increases in phosphorylation of IκBα and p65 can be detected as early as 3h post infection." (PMID 26367131, 2015). "However, while TNFf/f and NsTNF−/− mice produced equivalent chemokine concentrations, TNF−/− mice synthesised significantly higher levels (p < 0.01) of MIP-1α, MCP-1 and RANTES at 3 weeks post-infection." (PMID 26112704, 2015). "TNF-α production was, however, significantly lower in cultures from knockout macrophages compared to wt macrophages, indicating that these receptors are important for TNF-α production following infection with both strains." (PMID 25658098, 2015). "With no virtual vaccination or anti-TNF treatment, M. tuberculosis infections were contained in 99% of cases, and in one case out of 100, did not establish infection (Group 0)." (PMID 26779136, 2015). "It does not appear likely that this second-phase induction of TNF-α was due to the second-round of infection by progeny virus particles, as this second-phase induction of TNF-α was long-lasting." (PMID 26023919, 2015). "After treatment, when the infection had been controlled, the expression of TLR2 and TLR4 was still detected, and these TLRs may have been involved in the production of TNF-α, IFN-γ, IL-10 and NO, while TLR4 was involved in the production of IL-17." (PMID 25706930, 2015). "This UV inactivation did not inhibit the induction of TNF-α at two hours post infection, indicating that the integrity of the HCV genome was not essential for the induction of TNF-α at this early time point." (PMID 26023919, 2015).